PPP6C (protein phosphatase 6 catalytic subunit)
Description:
Catalytic subunit of protein phosphatase 6 (PP6). PP6 is a component of a signaling pathway regulating cell cycle progression in response to IL2 receptor stimulation. N-terminal domain restricts G1 to S phase progression in cancer cells, in part through control of cyclin D1. During mitosis, regulates spindle positioning. Down-regulates MAP3K7 kinase activation of the IL1 signaling pathway by dephosphorylation of MAP3K7. Also participates in the innate immune defense against viruses by desphosphorylating RIGI, an essential step that triggers RIGI-mediated signaling activation. Also regulates innate immunity by acting as a negative regulator of the cGAS-STING pathway: mediates dephosphorylation and inactivation of CGAS and STING1. CGAS dephosphorylation at 'Ser-435' impairs its ability to bind GTP, thereby inactivating it.
Synonyms: PP6C; PP6
Tractability: PROTAC: ubiquitination databases record sites on it; its protein half-life has been measured; a small molecule that binds it is known.
Target class: Enzyme; Hydrolase
Gene: Protein-coding gene on chromosome 9 (125,146,573 to 125,189,939, reverse strand). Ensembl gene ENSG00000119414.
Subcellular location: Mitochondrion; Cytoplasm
Pathways (Reactome):
Cell Cycle: Telomere Extension By Telomerase
Vesicle-mediated transport: COPII-mediated vesicle transport
Gene Ontology:
Molecular function: protein binding; protein serine/threonine phosphatase activity; hydrolase activity
Biological process: negative regulation of cGAS/STING signaling pathway; protein dephosphorylation; COPII vesicle coating; G1/S transition of mitotic cell cycle
Cellular component: cytoplasm; cytosol; mitochondrion; nucleoplasm
Genetic constraint (gnomAD): Loss-of-function variants: 7 observed, 31.19 expected, observed/expected ratio (o/e) 0.22, 90% interval 0.13 to 0.42. The upper end of that interval is the gene's LOEUF score, 0.42, which puts it in group 1 of 6, group 1 being the genes least tolerant of losing a copy. Missense variants: 173 observed, 324.44 expected, observed/expected ratio (o/e) 0.53, 90% interval 0.47 to 0.61. Synonymous variants: 103 observed, 109.95 expected, observed/expected ratio (o/e) 0.94, 90% interval 0.8 to 1.1.
Cancer hallmarks: genome instability and mutations (suppresses)
Homologues: Orthologues: chimpanzee PPP6C (100% identical), dog PPP6C (100% identical), guinea pig PPP6C (100% identical), pig PPP6C (100% identical), rabbit PPP6C (100% identical), mouse Ppp6c (99% identical), rat Ppp6c (99% identical), tropical clawed frog ppp6c (99% identical), zebrafish ppp6c (99% identical), macaque PPP6C (99% identical), Drosophila melanogaster PpV (75% identical), Caenorhabditis elegans pph-6 (61% identical). Paralogues in human: PPP4C (62% identical), PPP2CB (59% identical), PPP2CA (59% identical), PPP1CA (45% identical), PPP1CC (45% identical), PPP1CB (44% identical), PPP3CB (37% identical), PPP3CA (37% identical), PPP5C (37% identical), PPP3CC (37% identical), PPEF2 (30% identical), PPEF1 (30% identical).
Diseases named in the same sentence as PPP6C in open-access papers:
PPP6C is named in the same sentence as 52 diseases in open-access papers, as found by Europe PMC text mining. Sharing a sentence is not in itself a finding about the gene and the disease. The quoted sentences say what the papers report.
melanoma (25 papers, 2013 to 2026). A malignant, usually aggressive tumor composed of atypical, neoplastic melanocytes. "This recapitulated the phenotype of HeLa cells transiently depleted of PPP6C and melanoma cell lines with inactivating mutations in PPP6C, confirming that they were a suitable model to study loss of PP6 function." (PMID 36897279, 2023). "PPP6C is a phosphatase recurrently mutated in melanoma and has been reported as a major MEK phosphatase in cells exhibiting oncogenic ERK pathway activation." (PMID 36765773, 2023). "In this study, we have defined a novel function for PPP6C during melanocyte development and implicated PPP6C(R264C) in accelerated melanoma tumorigenesis." (PMID 35368039, 2022). "Recent studies suggest that PPP6C mutations affect its activity and participate in melanoma tumorigenesis through resulting MEK hyperphosphorylation." (PMID 35368039, 2022). "Using genetic approaches, we have explored the consequences of gain and loss of PPP6C function on melanocyte specification, proliferation, and the development of melanoma in vivo." (PMID 35368039, 2022). "All but one of these tumors containing a PPP6C(R264C) mutation were melanomas, suggesting a unique requirement for PPP6C in melanocytes." (PMID 35368039, 2022). "This study showed that in these patients the PPP6C mutations are frequent, occurring in 12% of sun-exposed melanomas, exclusively in tumors with mutations in BRAF or NRAS." (PMID 29156643, 2017). "Noteworthy, PPP6C mutations were more frequent in melanomas that were mutated for both BRAF and NRAS, while RAC1 mutations were more frequent in melanomas that were wild-type for both BRAF and NRAS." (PMID 24416617, 2013). "PPP6C is the only recurrently mutated serine/threonine phosphatase across all human cancers identified in sequencing studies and the recurrent R264C mutation occurs exclusively in melanoma." (PMID 35368039, 2022). "PPP6C mutations make melanoma cells susceptible to inhibition by Aurora kinase inhibitors." (PMID 32850962, 2020). "Like ANKRD52, which is mutated in 4.8% colorectal adenocarcinoma and 1.5% of all cancer types, PPP6C harbors recurrent and potentially driver mutations, such as the R264C mutation in 3% melanoma, which may disrupt PPP6C binding to ANKRD52 and thus the enzymatic activity." (PMID 34853298, 2021). "Moreover, PPP6C mutations in melanoma cells seems to induce an increased autophagy." (PMID 32850962, 2020). "A number of melanoma recurrent mutations have been reported in the literature in several genes including KIT, TERT, MAP2K1 and MAP2K2, RAC and PPP6C." (PMID 36765773, 2023). "Together, this data points to the role of PPP6C as a modulator of mitfa expression and suggests that expression of PPP6C(R264C) enhances melanoma initiation on an NRAS(Q61K) background." (PMID 35368039, 2022). "Together, these results define a unique role for PPP6C in melanocyte development and melanoma and place it upstream of regulating MITF expression and function." (PMID 35368039, 2022). "Expression of PPP6C(R264C) cooperated with oncogenic NRAS(Q61K) to accelerate melanoma initiation in zebrafish, consistent with a gain of function alteration." (PMID 35368039, 2022). "We detected mutations in six genes in the EVs (BRAF, NRAS, CDKN2A, STK19, PPP6C, and RAC), and at least one mutation was detected in all melanoma EV samples." (PMID 36531960, 2022). "Using a human melanoma cell line, we examined the requirement for PPP6C in proliferation and MITF expression." (PMID 35368039, 2022). "The level of pPLK1 was significantly higher in S/G2 phases in both AURKA over-expressing cell lines, and similarly elevated in ATM defective and PPP6C mutant melanoma cells." (PMID 33993200, 2021).
melanoma (continued). "One of these mutational networks presented in melanoma was the one containing MET besides CARD11, CBLB, PPP6C and RAC1." (PMID 34885093, 2021). "PPP6C encodes for the catalytic subunit of PP6 protein phosphatase complex, acting as a negative regulator of the melanoma oncogene CCND1 and as the major phosphatase of the Aurora kinase, and was found to be mutated in 9% of melanoma samples." (PMID 29156643, 2017). "As expected, this list included well documented frequent oncogenic drivers of melanoma, including hotspot mutations in BRAF, NRAS, RAC1, PPP6C, TRRAP, MAP3K5 and BCL2L12." (PMID 24913145, 2014). "In the case of the TCGA Pan-Cancer Atlas (448 melanoma samples in total), among the 35 BRAF V600K mutated samples, 5 also had the R264C mutation in PPP6C (14.3%), while only 2/158 (1.3%) samples carried concomitant BRAF V600E and PPP6C R264C mutations (Fisher’s Exact Test—p-value = 0.00242)." (PMID 36765773, 2023). "Melanoma cell lines are uniquely dependent on PPP6C expression for proliferation." (PMID 35368039, 2022). "Our data suggests that PPP6C may be a relevant drug target in melanoma and proposes a mechanism for its action." (PMID 35368039, 2022). "Additionally, the melanoma-specific oncogenic mutant PPP6C(R264C) led to a further reduction in expression of mitfa:GFP in vivo, suggesting that R264C is a gain of function mutation." (PMID 35368039, 2022). "In order to explore whether there was a link between the transcriptional program of MITF and PPP6C, we investigated 42 publicly available melanoma cell lines from the Broad Institute22." (PMID 35368039, 2022). "PPP6C is a well-known driver gene in melanoma that regulates cell cycle progression." (PMID 34795662, 2021). "A very recent study confirmed the frequent occurrence of PPP6C and RAC1 mutations in melanoma." (PMID 29156643, 2017). "The second group comprised of serine/threonine-protein phosphatase 6 catalytic subunit (PPP6C), DEAD-box helicase 3 X-linked (DDX3X), phosphatase and tension homology (PTEN), and ras-related C3 botulinum toxin substrate 1 (RAC1) genes, which showed mutations in 5 to 9% melanoma tissues." (PMID 33256110, 2020). "In conclusion, PPP6C mutations in melanoma may lead to new targeted approaches, such as specific PPP6 inhibitors, but at now, no trials are ongoing." (PMID 32850962, 2020). "Recently, a tight interaction between PPP6C-AurkA and MAPK pathways in controlling proliferative activity and apoptosis in melanoma cells has been demonstrated, contributing to increase the levels of tumor heterogeneity and conferring a resistance signature in BRAF- and NRAS-mutated melanomas." (PMID 30218391, 2018). "In addition, three candidate genes, MYCN, PPP6C, and STK19, known to be associated with melanoma development, might be considered as new BCC driver genes." (PMID 29165358, 2017). "Our data reveals a novel role for PPP6C in regulating the activity of MITF in melanocytes and melanoma." (PMID 35368039, 2022). "More recently, deep-sequencing approaches of melanoma samples of different melanoma types highlighted new melanoma driver genes such as PREX2, PPP6C, and RAC1." (PMID 24416617, 2013). "Similarly, chromosome 9 and 10, commonly deleted in these cancers, contain several important suppressor genes such as CDKN2A and PTEN in glioma; XPA, PPP6C, and CDKNA in melanoma; PTCH1 and SUFU in medulloblastoma." (PMID 41537310, 2026). "After observing that mitfa transcriptional activity is negatively affected by PPP6C expression, we sought to identify the changes that might occur when PPP6C expression is reduced in an MITF-low melanoma." (PMID 35368039, 2022). "We identified PPP6C, a serine/threonine phosphatase, as a key regulator of MITF in melanoma." (PMID 35368039, 2022).
melanoma (continued). "Moreover, genes KDM5D, UTY, and NF1 have demonstrated gender differences in lung cancer, while PPP6C and IGF1R exhibit sex-biased expression in melanoma, and the NRAS gene may play sex-specific roles in acute myelogenous leukemia." (PMID 39541191, 2024).
viral infection (4 papers, 2020 to 2022). "PPP6C has been implicated in DNA damage repair, oocyte, and lymphocyte development, virus infection, innate immune responses, carcinogenesis, etc." (PMID 35842423, 2022). "For example, cGAS is found to be unphosphorylated at the resting state to restrain its inappropriate activation by associating with PPP6C, and this interaction is alleviated upon viral infection, allowing for cGAS phosphorylation that primes cGAS activation." (PMID 35795661, 2022).
cervical cancer (3 papers, 2021 to 2024). A primary or metastatic malignant neoplasm involving the cervix. "The METTL3-induced transcription factor interferon regulatory Factor 5 (IRF5) promotes proliferation, migration, invasion, and angiogenesis in cervical cancer (CC) cells by upregulating the protein phosphatase 6 catalytic subunit (PPP6C)." (PMID 39295872, 2024). "In fact, PPP6C protein expression was significantly upregulated in glioma and cervical cancer." (PMID 34587164, 2021).
glioma (3 papers, 2021 to 2026). A benign or malignant brain and spinal cord tumor that arises from glial cells (astrocytes, oligodendrocytes, ependymal cells). "Among all PPPcs, only PPP6C has been explicitly identified as an oncogene in previous studies; high expression of PPP6C was observed in glioma tissues." (PMID 33270085, 2021). "PPP6C protein expression was significantly increased in glioma tissues." (PMID 34587164, 2021).
breast carcinoma (2 papers, 2021 to 2022). "The alterations of PPP1CA, PPP3CA, PPP3CB and PPP6C were significantly associated with the prognosis of breast cancer." (PMID 34964699, 2022). "Among the genes with low expression in breast cancer tissues, PPP3CB and PPP6C were positively associated with CD8 + T cell, macrophage and neutrophil infiltration." (PMID 34964699, 2022). "PPP2CB, PPP3CA, PPP3CB, PPP3CC and PPP6C were significantly expressed at lower levels in breast cancer tissues." (PMID 34964699, 2022). "In the Oncomine database, when compared with normal breast tissues, PPP1CA, PPP2CA, PPP4C and PPEF1 were significantly elevated in breast cancer tissues, while PPP1CB, PPP2CB, PPP3CA, PPP3CB, PPP3CC and PPP6C were significantly decreased in breast cancer tissues." (PMID 34964699, 2022).
pancreatic cancer (2 papers, 2021). "Results of the present study suggest that PPP1CA, PPP1CB, PPP2CA, PPP2CB, and PPP3CA have deleterious effects but PPP3CB, PPP5C, and PPP6C have beneficial effects on pancreatic cancer." (PMID 33270085, 2021). "However, the survival analysis showed that PPP6C seemed to be a favorable prognostic factor with regard to both transcription and protein levels in pancreatic cancer." (PMID 33270085, 2021). "Among all these PPPcs, only PPP6C was explicitly identified as an oncogene in previous reports, although other PPPs or PPPcs also showed important roles in the pathogenesis and progression of pancreatic cancer." (PMID 33270085, 2021). "In recent years, it has been reported that PPP1CA, PPP1CB, PPP2CA, PPP2CB, and PPP3CA accelerate the progression of pancreatic cancer, while PPP3CB, PPP5C, and PPP6C hinder PAAD progression." (PMID 34125004, 2021). "In contrast, patients with pancreatic cancer and high transcription levels of PPP3CB, PPP5C, PPP6C, and PPEF2 seemed to have better prognosis." (PMID 33270085, 2021). "Data from THPA and patients with pancreatic cancer enrolled in our hospital also confirmed the prognostic value of PPP1CA, PPP1CB, PPP2CA, PPP2CB, PPP3CA, PPP3CB, and PPP6C at the protein level." (PMID 33270085, 2021). "In addition, only PPP3CB and PPP6C showed favorable prognostic values with regard to protein level, whereas PPP1CA, PPP1CB, PPP1CC, PPP2CA, PPP2CB, and PPP3CA showed unfavorable prognostic values in pancreatic cancer (P<0.05)." (PMID 33270085, 2021).
papilloma (2 papers, 2021 to 2024). A benign epithelial neoplasm that projects above the surrounding epithelial surface and consists of villous or arborescent outgrowths of fibrovascular stroma. "We assessed Ppp6c function in a mouse model of skin carcinogenesis and found that loss of Ppp6c in keratinocytes promotes 7,12‐dimethylbenz[a]anthracene‐induced papilloma formation and ultraviolet B‐induced carcinogenesis." (PMID 38318686, 2024).
psoriasis (2 papers, 2015 to 2022). An autoimmune condition characterized by red, well-delineated plaques with silvery scales that are usually on the extensor surfaces and scalp. "miR-31 directly targets ppp6c, an essential element regulating cell cycle, which has been shown to be diminished in the epidermis of lesional skin from patients with psoriasis." (PMID 26138368, 2015). "We next investigated the ppp6c expression in the epidermis derived from lesional skin of human patients with psoriasis." (PMID 26138368, 2015). "Thus, our data identify NF-κB-induced miR-31 and its target, ppp6c, as critical factors for the hyperproliferation of epidermis in psoriasis." (PMID 26138368, 2015). "Thus, our data again indicate that miR-31 and its target ppp6c are critical factors in epidermal hyperplasia in psoriasis." (PMID 26138368, 2015). "In an IL-23-mediated mouse model of psoriasis, the ppp6c expression was increased more than ∼8.0-fold at the mRNA levels and 12.0-fold at the protein levels in the ear epidermis of the cKO mice injected with IL-23 compared with that of the miR-31fl/fl controls." (PMID 26138368, 2015). "We showed that ppp6c expression is diminished in the epidermis of lesional skin from patients with psoriasis, and that knockdown of ppp6c by siRNA or shRNA results in an enhanced percentage of proliferating keratinocytes in vitro and promotes psoriasiform skin disease in the IMQ-induced mouse model." (PMID 26138368, 2015). "The role of ppp6c in keratinocyte hyperproliferation and in the pathogenesis of psoriasis is not known." (PMID 26138368, 2015).
skin melanoma (2 papers, 2021 to 2023). "This intronic variant of the protein phosphatase 6 catalytic subunit (PPP6C) is an eQTL for PPP6C, a gene linked to various cancers, including skin melanoma and lung squamous cell carcinoma." (PMID 37985822, 2023).
autoimmune disorders (1 paper, 2020). "Dephosphorylation of STING by PPP6C helps prevent the sustained production of STING-dependent cytokines, which would otherwise lead to severe autoimmune disorders." (PMID 32753499, 2020). "Therefore, PPP6C helps prevent the sustained production of STING-dependent cytokines, which would otherwise lead to severe autoimmune disease." (PMID 32753499, 2020).
colitis (1 paper, 2022). Inflammation of the colon. "In addition, we employed a DSS-induced colitis mouse model to further investigate the role of PPP6C in regulating the inflammatory diseases." (PMID 35842423, 2022). "It is worth noting that whether necroptosis or the kinase activity of RIPK1 is necessary for DSS-induced colitis is still debatable, so we speculate that PPP6C might play a more complex role in regulating tissue injury and inflammation beyond its ability to promote necroptosis." (PMID 35842423, 2022).
depression (1 paper, 2022). "In contrast with OPRM1, variants in PPP6C have been associated with numerous brain- and SUD-related phenotypes, notably opioid medication use, alcohol consumption, numerous smoking phenotypes, and depression among others." (PMID 36207451, 2022).
female infertility (1 paper, 2021). Diminished or absent ability of a female to achieve conception. "Our lab previously reported that a conditional knockout of PPP6C in oocytes from growing follicles resulted in female subfertility, and a conditional knockout of PPP6C in oocytes from the primordial follicle stage, caused female infertility." (PMID 34580275, 2021).
hepatocellular carcinoma (1 paper, 2024). A malignant tumor that arises from hepatocytes. "Conversely, certain other microRNAs displayed a reverse pattern of expression: MiR-373 acts as an oncogenic miRNA in hepatocellular carcinoma by promoting cell proliferation and the G1/S cell cycle transition through downregulation of the tumor suppressor PPP6C." (PMID 39876897, 2024).